PTH (parathyroid hormone)
Diseases named in the same sentence as PTH in open-access papers (continued):
Sharing a sentence is not in itself a finding about the gene and the disease.
Hypocalcemia (continued). "These type of surgical interventions are recommended to preserve the parathyroid hormone production and to avoid postoperative severe hypocalcemia." (PMID 36984449, 2023). "Afterwards, mild hypocalcemia and hyperphosphatemia with elevated PTH levels suggestive of PTH resistance were detected." (PMID 37635873, 2023). "Low blood calcium levels (hypocalcaemia) trigger the parathyroid glands to produce parathyroid hormone (PTH) to increase calcium levels." (PMID 38068758, 2023). "The major biochemical alterations of CKD-MBD encompass hyperphosphatemia, hypocalcemia, decreased serum vitamin D level, and increased parathyroid hormone (PTH) secretion." (PMID 37878613, 2023). "Hypoparathyroidism is a rare endocrine disease characterized by hypocalcemia with low or undetectable parathyroid hormone (PTH) concentrations." (PMID 37335755, 2023). "In our study, hypocalcaemia and vitamin D deficiency appeared as early as in CKD stage 4, and despite the phosphate, the PTH and ALP levels still fell within the normal reference intervals." (PMID 37102048, 2023). "All these factors and mechanisms will ultimately result in hypocalcemia and stimulate the increased secretion of PTH." (PMID 38075043, 2023). "PTH resistance is characterized by hypocalcemia and hyperphosphatemia in the presence of elevated PTH concentrations, resulting in pseudohypoparathyroidism, which is subdivided into different types according to its different pathogenesis and phenotype." (PMID 37908988, 2023). "Clinical symptoms requiring treatment were observed in 76% of patients with a decline in biochemical PTH, while in the group of patients with hypocalcemia, they affected 29.17%." (PMID 37626794, 2023). "The release of PTH and synthesis of 1,25-dihydroxyvitamin D3 (1,25D) from 25-hydroxyvitamin D3 are key endocrine events that counteract hypocalcemia, leading to urinary and intestinal Ca2+ (re)absorption and bone Ca2+ mobilization." (PMID 37240030, 2023). "Low PTH levels, as well as biochemical and clinical evidence of hypocalcemia, mucocutaneous candidiasis, abnormally misaligned teeth, and discolored nails, led us to suspect APS-1(APECED) as the cause of Fahr’s syndrome." (PMID 37456991, 2023). "A former systematic review concluded that the perioperative PTH concentration and preoperative vitamin D level are useful biochemical predictors of post-thyroidectomy hypocalcemia." (PMID 36835843, 2023). "The median PTH serum concentration prior to surgery in dogs who developed hypocalcaemia post‐surgery was 232 (IQR 108–421) compared to a median of 81.5 (IQR 58.5–145.0) for eucalcaemic or hypercalcaemic dogs post‐surgery." (PMID 38053473, 2023). "The use of Ca as a hypocalcemia predictor has fallen into disuse, partly due to a slower drop time than PTH, with its lowest values between the second and third day PO." (PMID 36651710, 2023). "In Ahn’s study, the criteria for transient hypoparathyroidism were serum parathyroid hormone levels below baseline, need for oral calcium supplementation or hypocalcemia symptoms." (PMID 36733809, 2022). "The definitions of PH included reduced PTH levels only, hypocalcaemia only, reduced PTH or hypocalcaemia or a combination of both." (PMID 36050906, 2022). "Because of this, the CaSR has been addressed as a key factor responsible for hypocalcemia and low levels of PTH that are commonly found in critically ill patients under sepsis or after burn injury." (PMID 36467702, 2022). "On the contrary, in hypocalcemia conditions, lowered intracellular calcium leads to increased PTH production and secretion." (PMID 36293076, 2022). "A first hint about this perspective comes from a recent cross-sectional study, where PTH levels were found to be low in roughly 40% of COVID-19 patients with hypocalcemia, hence implying a defect in parathyroid functionality." (PMID 36467702, 2022).
Hypocalcemia (continued). "Patients in whom a greater number of parathyroids had been identified had a significantly higher incidence of biochemical and symptomatic hypocalcaemia, and significantly lower postoperative PTH levels, than patients with fewer glands identified." (PMID 34406491, 2022). "Low parathyroid hormone levels, which lead to hypocalcemia, were also proposed as the etiology of enamel hypoplasia and enamel opacities." (PMID 35455492, 2022). "Both presented with neonatal hypocalcemia, elevated serum phosphorus concentration, PTH values constantly suppressed or undetectable (<3 ng/mL), and low vitamin D values (13 ng/mL and 15 ng/mL in P4 and P5 patients, respectively)." (PMID 35407632, 2022). "Hypoparathyroidism (HypoPT) is a rare disorder characterized by hypocalcemia in the presence of a low or inappropriately normal parathyroid hormone level." (PMID 36161671, 2022). "As expected, AH-1 treatment normalized rickets phenotypes, including hypocalcemia and osteodysplasia by reducing plasma PTH and 1,25(OH)2D3 to normal levels." (PMID 35869242, 2022). "Hypoparathyroidism (hypoPT), defined by hypocalcemia from inappropriately low parathyroid hormone (PTH) levels, is currently one of the most common and debilitating complications of neck surgery worldwide." (PMID 35310601, 2022). "In hypocalcemia, high circulating PTH triggers the osteoclast nuclear factor‐κB pathway to stimulate bone resorption, thereby releasing Ca2+, Pi, and Mg2+ into the circulation." (PMID 35385223, 2022). "This study aimed to investigate the role of early postoperative PTH and calcium blood levels and post/pre-surgery PTH and calcium ratios as predictors for the development of symptomatic hypocalcemia within 24 h post thyroidectomy." (PMID 35566513, 2022). "When she was 21 years old, she came to our clinic and was diagnosed with sporadic PHP1b on the basis of hypocalcemia, high PTH levels, and (epi)genetic testing." (PMID 36465610, 2022). "In the kidney, in response to hypocalcemia and hyperphosphatemia, PTH tends to enhance proximal tubule calcium reabsorption and phosphate excretion." (PMID 36293076, 2022). "One study indicated a similar diagnostic accuracy of intraoperative PTH measurements and ICG perfusion assessment for the prediction of postoperative hypocalcemia (0.84 and 0.92, respectively)." (PMID 35330139, 2022). "Among the subjects with elevated serum PTH levels, some also had hypophosphatemia, but very few had hypocalcemia." (PMID 35140619, 2022). "In the whole cohort, hypocalcaemia and hyperphosphatemia were observed in 27 of the 31 patients and increased serum PTH levels in 31 of the 31 patients." (PMID 36213284, 2022). "Hypoparathyroidism (HypoPT) is a rare endocrine disease which is characterized by hypocalcaemia and undetectable or inappropriately low serum parathyroid hormone (PTH)." (PMID 35751804, 2022). "The main alterations of CKD–MBD encompass hyperphosphatemia, hypocalcemia, low serum levels of vitamin D, and an increased secretion of parathyroid hormone (PTH) from the parathyroid glands (secondary hyperparathyroidism, SHPT)." (PMID 36293076, 2022). "Decreased (iMg) is a cause of persistent hypocalcemia through impaired PTH secretion, end-organ parathyroid hormone (PTH) responsiveness and decreased synthesis of 1,25-dihydroxyvitamin D3 that has been observed in horses and humans." (PMID 35739816, 2022). "Eighteen women had hypocalcemia with an even distribution between categories of vitamin D levels, only four of these had increased PTH level." (PMID 35684109, 2022). "The purpose of the present study was to examine utility of POD1 PTH levels as predictor of post-thyroidectomy symptomatic hypocalcaemia at our institution, and to determine cut-off levels for selection of patients for early discharge." (PMID 35247092, 2022). "Transcription of the PTH gene is stimulated mainly by hypocalcemia, but also by hyperphosphatemia, uremia, and is suppressed by 1,25(OH)2D." (PMID 36246903, 2022).
Hypocalcemia (continued). "Laboratory assessments of the patient revealed hypokalemia, hypocalcemia and hyperphosphatemia despite elevated PTH levels." (PMID 35410271, 2022). "Since PTH is one of the most essential peptide hormones for calcium and phosphorus homeostasis, patients with PHP suffer from hypocalcemia, hyperphosphatemia, and high serum PTH level." (PMID 36465610, 2022). "For PTH levels 10–14 pg/ml and calcium ≥ 2.0 mmol/l, the incidence of symptomatic hypocalcaemia and need for intravenous calcium was 11.7% (7/60)." (PMID 35247092, 2022). "We reported gender, age, estimated glomerular filtration rate, creatinine, preoperative 25-hydroxyvitaminD, serum pre- and postoperative calcium, pre- and postoperative PTH levels and transient postoperative hypocalcemia occurrences." (PMID 34564834, 2022). "The present findings are consistent with those of several previous studies, in which a high preoperative PTH concentration was found to be a predictor of postoperative hypocalcemia." (PMID 36531501, 2022). "Pseudo-hypoparathyroidism type 1a (PHPT-1a) is a rare condition, characterized by resistance to the parathyroid hormone (PTH), as well as to many other hormones, and resulting in hypocalcemia, hyperphosphatemia, and elevated PTH." (PMID 36553004, 2022). "As in the case described, severe and prolonged (more than 4 days) hypocalcemia in the period immediately after parathyroid surgery is a common event, particularly if high calcium and PTH pre-operative levels are present." (PMID 35872978, 2022). "At the 12-month follow-up the patient demonstrated hypocalcaemia substituted with oral calcium, but had normal PTH levels." (PMID 36515670, 2022). "The increased PTH gene expression in experimental SHP induced by either uremia or prolonged hypocalcemia is due to post-transcriptional mechanisms that alter PTH mRNA stability and levels." (PMID 35208186, 2022). "Patients with transient postoperative hypocalcemia had lower levels of postoperative PTH (p < 0.001) and more frequently normal or deficitary 25-hydroxyvitaminD levels (p = 0.05)." (PMID 34564834, 2022). "Aluminum accumulates in the parathyroid glands, reduces the parathyroid response to hypocalcemia, and prevents the release and synthesis of parathyroid hormone (PTH)." (PMID 35070453, 2022). "Enhanced PTH mRNA stability is the major mechanism that increases PTH gene expression in experimental SHP due to either dietary induced prolonged hypocalcemia or uremia." (PMID 35208186, 2022). "Hypoparathyroidism is characterized by decreased parathyroid hormone (PTH) secretion due to impaired PTH activity, presenting hypocalcemia and hyperphosphatemia." (PMID 36686468, 2022). "Subsequently, low calcitriol levels and hypocalcemia induced by increasing FGF23 levels indirectly stimulate PTH synthesis and release in the parathyroid via VDR and CaSR, overriding the inhibitory action of FGF23." (PMID 35269640, 2022). "Patients with pseudohypoparathyroidism (PHP) have hypocalcemia and hyperphosphatemia, similar to those of hypoparathyroidism, but have high levels of biologically active PTH." (PMID 36246903, 2022). "Hypocalcemia, in turn, augments increased production of parathyroid hormone (PTH), thus leading to secondary hyperparathyroidism." (PMID 36014808, 2022). "The eponymous bone disorders in CKD–MBD are a consequence of the hypocalcemia and PTH overproduction inducing excessive bone resorption through osteoclast stimulation." (PMID 35893866, 2022). "While all cases in our study presented with hypocalcemia, hyperphosphatemia, and increased serum PTH, only two (cases 1 and 5) were presented with typical AHO features, which suggested a diagnosis of PHP1a/1c." (PMID 35992960, 2022). "An increase in PTH secretion is triggered by hypocalcaemia, hyperphosphataemia, or a decreased active vitamin D." (PMID 36672533, 2022).
Hypocalcemia (continued). "There is a high frequency of anemia, hypocalcemia, hyperphosphatemia, and changes in PTH levels, showing the need for urgent intervention by public health managers so that these patients receive better quality health care." (PMID 35442270, 2022). "Synthesis of 1-α-hydroxylase is induced by hypocalcemia and PTH, whereas 24-hydroxylase activity is potentiated by hyperphosphatemia and FGF-23." (PMID 36293076, 2022). "In turn, excess serum phosphorus increases PTH secretion, as well as results in hypocalcaemia (phosphorus forms complexes with calcium) and stimulates fibroblast growth factor-23 (FGF-23)." (PMID 36672533, 2022). "Conditions such as hypocalcemia or uremia can increase the amount of PTH mRNA by modifying the activity of mRNA binding proteins." (PMID 36246903, 2022). "Inhibition of 1,25-dihydroxy vitamin D induces hypocalcemia, stimulating the parathyroid gland to release PTH at persistent circulating levels." (PMID 36232497, 2022). "Hypoparathyroidism (HypoPT) is a rare condition characterized by reduced parathyroid hormone (PTH) levels resulting in hypocalcemia and hyperphosphatemia." (PMID 36557317, 2022). "In conclusion, the combination of preoperative low Ca, high ALP, and high PTH has a good predictive value for hypocalcemia following PTX in patients with SHPT." (PMID 36531501, 2022). "Post-transcriptional mechanisms also mediate the increased PTH gene expression by hypocalcemia and uremia in SHP." (PMID 35208186, 2022). "Phenotypic data indicated that the patient had hypomagnesemia, poor parathyroid hormone response, and resultant hypocalcemia." (PMID 35692977, 2022). "When the parathyroid glands are compromised, PTH production and release are jeopardized, failing to rise in response to hypocalcemia." (PMID 36382754, 2022). "Hypocalcemia and hyperphosphatemia are drivers for elevated parathyroid hormone levels, which were also observed in the population." (PMID 36819194, 2022). "The PTH from the parathyroid glands counteracts hypocalcemia by stimulating osteoclasts to initiate calcium resorption from the bone." (PMID 35893866, 2022). "In case of parathyroidectomy, and limited external calcium supply, death ensues within hours from severe hypocalcemia and hyperphosphatemia, unless treated with PTH." (PMID 36246903, 2022). "A diagnosis of PTH resistance was made on the basis of severe hypocalcemia, hyperphosphatemia, elevated PTH and normal vitamin D levels on blood sample." (PMID 35846276, 2022). "A rare disorder of impaired or inadequate PTH secretion, hypoparathyroidism, leads to hypocalcemia, hyperphosphatemia, and the clinical consequences described herein." (PMID 36153665, 2022). "In contrast, 1,25(OH)2D is stimulated by (absolute or relative) hypocalcemia, (absolute or relative) hypophosphatemia, and parathyroid hormone (PTH)." (PMID 35710560, 2022). "Our study used PTH ≤10 pg/mL and hypocalcemia as a criterion to define hypoparathyroidism after thyroidectomy." (PMID 36644104, 2022). "All patients presented with hypocalcemia, hypophosphatemia, increased serum alkaline phosphatase and parathyroid hormone, and high RSS at diagnosis." (PMID 36405822, 2022). "Pseudohypoparathyroidism (PHP) is one group of rare clinical syndromes characterized by hypocalcemia, hyperphosphatemia, and increased serum concentration of parathyroid hormone (PTH) combined with unique clinical features." (PMID 35992960, 2022). "Thirdly, activation of the systemic immune response after ICH leads to PTH-vitamin D axis dysfunction, low serum Ca levels, or hypocalcemia." (PMID 36698873, 2022). "This hypocalcemia increases the secretion of parathyroid hormone (PTH), stimulates parathyroid cell size and proliferation, and induces a loss of the negative-feedback loop between extracellular calcium and PTH." (PMID 35323709, 2022). "In the present study, we identified preoperative PTH, Ca, and ALP as risk factors for severe hypocalcemia during the early postoperative period." (PMID 36531501, 2022).
Hypocalcemia (continued). "In an interesting but older metanalysis, it was reported that early post-thyroidectomy PTH levels lack the accuracy to predict hypocalcemia and enable early (within 24 h) discharge." (PMID 35566513, 2022). "Hypoparathyroidism is a rare endocrine condition characterized by low or insufficient levels of circulating parathyroid hormone (PTH), leading to hypocalcemia (low levels of serum calcium)." (PMID 36644104, 2022). "The results of this analysis identified PTH, Ca, and ALP (P<0.05) as independent risk factors for hypocalcemia following PTX in patients with SHPT." (PMID 36531501, 2022). "Parathyroid-specific deletion of the miRNA maturating enzyme Dicer in PT-Dicer−/− mice results in a muted increase in PTH expression by both hypocalcemia and uremia, indicating that parathyroid miRNAs are crucial for the stimulation of the parathyroid in SHP." (PMID 35208186, 2022). "Hypocalcemia due to low parathyroid hormone (PTH) levels can be classified as transient if it lasts less than six months or permanent if it persists for more than six months." (PMID 35566513, 2022). "The body’s compensatory elevation of parathyroid hormone (PTH) is insufficient; subsequently the calcium supply cannot increase, resulting in a state of hypocalcemia." (PMID 36292790, 2022). "The common TEAEs that occurred in this study were generally consistent with those listed on the label of denosumab, such as hypocalcemia, hypophosphatemia, increased PTH levels, and arthralgia." (PMID 35140619, 2022). "In order to correct this hypocalcemia, PTH exerts many biological actions on different target organs, mainly through activating its receptor, PTH1R." (PMID 36293083, 2022). "The typical serum abnormalities presented by patients with SHPT are hyperphosphatemia, hypocalcemia and elevated PTH." (PMID 36142318, 2022). "The most frequent AEs were elevated serum PTH level (83.3%), hypocalcemia (54.2%), and hypophosphatemia (45.8%)." (PMID 35784742, 2022). "As a result, low calcitriol levels and hypocalcemia promote PTH synthesis and release via VDR and CaSR in parathyroid, overriding the inhibitory effect of FGF23." (PMID 35269640, 2022). "Hyperphosphatemia promotes hyperparathyroidism through the induction of hypocalcemia, decreased formation of 1,25(OH)2D3, and increased PTH gene expression." (PMID 36293076, 2022). "In contrast, in patients with PTH of ≥1.3 pmol/L, the calcium level, calcium rate of ≤2.10 mmol/L, number of patients with symptomatic hypocalcemia were comparable among the three groups." (PMID 36091150, 2022). "Most authors use biochemical definitions for PH, such as PTH levels (with different cut-offs) or postoperative hypocalcemia." (PMID 35683589, 2022). "Laboratory tests revealed PTH resistance in all six patients with three cases (P3, P4, P5) presenting with hypocalcemia, five (P1, P3, P4, P5, P6) with TSH resistance, and two cases (P1, P4) with mildly elevated plasma ACTH." (PMID 35296306, 2022). "During hypocalcemia, PTH solely triggers the bone resorption process, which increases plasma Ca2+, Pi, and Mg2+ levels." (PMID 35385223, 2022). "It is a heterogeneous group of disorders characterized by hypocalcemia, hyperphosphatemia, increased serum concentration of parathyroid hormone (PTH), and insensitivity to the biologic activity of PTH." (PMID 35600030, 2022). "Pseudohypoparathyroidism type 1 (PHP1) is a rare genetic disorder, in which affected patients manifest hypocalcemia and hyperphosphatemia despite elevated serum parathyroid hormone (PTH) levels." (PMID 35497370, 2022). "The correlation between BMI and preoperative PTH and BMI and the occurrence of postoperative hypocalcemia, can be explained by the level of vitamin D, which is correlated to BMI." (PMID 36268338, 2022). "Surprisingly, these mice fail to increase serum PTH in response to hypocalcemia or uremia, indicating a role for miRNAs in parathyroid stimulation." (PMID 35208186, 2022).